SPP1 (secreted phosphoprotein 1)
Diseases named in the same sentence as SPP1 in open-access papers (continued):
Sharing a sentence is not in itself a finding about the gene and the disease.
tumor (continued). "To validate the spatial localization of POSTN+ CAFs and SPP1+ macrophages in the TME of NSCLC, we performed multiplexed IHC (mIHC) using FFPE tumour samples from fifteen NSCLC patients." (PMID 38115703, 2023). "Spp1 results were confirmed in real-time PCR analysis performed on 15 MPM samples; mRNA levels were significantly higher in tumor tissues compared to un-diseased tissues." (PMID 37398648, 2023). "The results of EdU staining assays showed that si-SPP1 and si-CSF1 decreased tumor cell proliferation." (PMID 37097499, 2023). "The Ma1 cluster characteristically expressed SPP1, as well as high expression of marco which can promote M2 macrophage polarization, meanwhile CXCL5, which promotes tumor metastasis, was also highly expressed in this subpopulation." (PMID 37675100, 2023). "The results showed that most signal flows in the JAG1 positive samples was stronger, including: SPP1 and SELL signal flow, which related to immunosuppressive microenvironment, and tumor angiogenesis-related pathway: NOTCH, VEGF, FGF signal flows." (PMID 36923423, 2023). "The effects of CCL18 on tumor cells were similar to SPP1 TAM, implying that this CCL8+ macrophage subpopulation was originated from SPP1+ TAMs." (PMID 38347955, 2023). "The relationship between CK17 tumor expression and CXCL9/SPP1 expressing macrophages should be explored further." (PMID 37835599, 2023). "On the other hand, the results showed that, for LUSC tumor samples, CDH2, SPP1, and TNC were significantly upregulated and FN1, CYR61, SERPINA1, and IL6 were significantly downregulated compared to their respective controls." (PMID 37887075, 2023). "The results showed that the expression patterns of SPP1 and CSF1 in normal and tumor tissues were most similar to those of ITGAV and PLAUR, respectively." (PMID 37097499, 2023). "The qRT-PCR results revealed a significant upregulation of CBX2, SPP1, and ZC4H2, alongside a notable downregulation of FMO3 in tumor tissues." (PMID 37287752, 2023). "Nonetheless, SPP1, APOE, and TREM2 manifested more average fold changes than the C1Q genes and were expressed in more tumor cells than normal tissue cells." (PMID 37187751, 2023). "In line with this, enrichment of high PD-L1 expressing IFIT1+, SPP1+ and CCL4+ TANs in HCC tumours correlated with a poorer prognosis indicating a pro-tumour role for these clusters." (PMID 37534829, 2023). "APOC1+SPP1+ TAM secretes SPP1, which binds to ITGF1 secreted by CAFs to remodel the tumor microenvironment." (PMID 37333982, 2023). "Significant disparities in protein expression levels of CBX2, SPP1, ZC4H2, and FMO3 were detected between tumor tissues and matched para-tumor tissues." (PMID 37287752, 2023). "SPP1+ macrophages expressed MRC1 (M2 marker), and TREM2 which correlates with tumor infiltrating CD8 exhaustion." (PMID 37633924, 2023). "We revealed that Macro-SPP1 and Fib-APSN are preferentially enriched in the tumor boundary across cancer types." (PMID 36806082, 2023). "Since the Macro-SPP1 and Fib-APSN enriched tumor boundaries contribute to the formation of desmoplastic boundary structure related to tumor immune excluded microenvironment (TIEM), these cells potentially limit T cell infiltration into malignant regions." (PMID 36806082, 2023). "We identified Macro-SPP1 and Fib-APSN, the major cellular constituents of the tumor boundary, which exhibited strong interactions with each other and significantly with tumor cells." (PMID 36806082, 2023). "We found that BMX and FYN had lower expression levels in HCC tumour tissues, whereas KPNA2, PFKFB4, and SPP1 had higher expression levels in HCC tumour tissues." (PMID 36873244, 2023). "The upregulation of SPP1 due to hypermethylation induces resistance to the 1st and 2nd generation EGFR-TKI and influences tumor immune infiltration in tumor tissues and cell lines." (PMID 37152062, 2023).
tumor (continued). "To further demonstrate the role of SPP1 in HCC, we explored the distribution of SPP1 expression across different types of tumor and normal tissues in TCGA." (PMID 37386390, 2023). "Additional Nanostring analysis allowed us to reveal that SPP1 is differentially expressed in immune CD45+ and tumor cytokeratin (CK)+ regions." (PMID 36895491, 2023). "Secreted phosphoprotein 1 (SPP1), an acidic glycoprotein known as osteopontin (OPN), participated in EMT and tumor metastasis." (PMID 38041130, 2023). "We further identified the top 100 specifically expressed genes in the tumor boundary of the three CRC ST samples which overlapped significantly, and included SPP1, MMP11, and COL1A1." (PMID 36806082, 2023). "We also observed that SPP1 gene mainly expressed in immune cells, whereas the CD44 mainly expressed in tumor cells." (PMID 37441593, 2023). "The results revealed that SPP1, COMP, THBS2, SERPINE1, and COL11A1 were highly expressed in tumor tissues, while MYH11, TAGLN, and CNN1 were lowly expressed." (PMID 36999888, 2023). "Comparison of the gene expression of TREM2+ TAMs between the tumor and adjacent normal tissue revealed that TREM2, SPP1, APOE, C1QA, C1QB, and C1QC were upregulated in tumors, which was consistent with the results for GSE160269." (PMID 37187751, 2023). "Elevated RUNX2 levels can transcriptionally activate genes that mediate tumor progression and metastasis, including the RUNX2 target gene osteopontin (OPN/SPP1) in OS." (PMID 37240338, 2023). "A subtype of TAM with a unique feature called SPP1+ macrophages was reported recently to carry immunosuppressive property and positively correlated with EMT markers as a potential target for anti-tumor growth and metastasis." (PMID 35365629, 2022). "In contrast, the HCLs showed higher expression of all investigated tumor markers in comparison to PHCs and HCC-PHHs, except for SPP1." (PMID 36077764, 2022). "Because FAP+ fibroblasts and SPP1+ macrophages were closely involved in the hypoxia-induced pathway, we hypothesized the presence of a stromal cell-mediated network localized in the hypoxic region of the tumor that links macrophages and MSCs, which collaborate to exacerbate the CRC microenvironment." (PMID 35365629, 2022). "In line with a pro-tumoral role of secreted OPN, OPL239 Spp1-IRES-Green cells showed a significant increase in tumor take, assessed as CD19 + GFP + population in the spleen, in comparison to control and iOPN-overexpressing cells." (PMID 36503430, 2022). "PPI analysis revealed 22 genes for MECa and 63 for AdCC that were validated by Kaplan–Meier that showed FN1 and SPP1 for MECa, and EGF and ERBB2 for AdCC as more significant candidate genes for each neoplasm." (PMID 36146635, 2022). "We found high concordance among three different cohorts with pairs to be assigned to Cluster 1 or Cluster 2, especially for tumor-TAM-derived pairs in Cluster 1, i.e., LGALS9-SLC1A5 and SPP1-PTGER4 pairs." (PMID 36476645, 2022). "Our study indicates that a unique tumor-macrophage link via ligand–receptor interactions from LGALS9-SLC1A5 and/or SPP1-PTGER4 signaling pairs appears a stable molecular feature to define ITH linked to overall survival of patients with HCC." (PMID 36476645, 2022). "SPP1 may be considered as a general marker of cancer progression, would be valuable in combination with other biomarkers to guide patient stratification and treatment strategies, and would be an attractive therapeutic target due to its multiple roles in promoting tumor aggressiveness." (PMID 36110938, 2022). "In addition, SPP1 could predict the response of tumor immunotherapy." (PMID 35067176, 2022).
tumor (continued). "Then, we picked out 8 HAIRGs (VEGFA, CTNNB1, PPARG, HSP90AA1, HMOX1, LGALS3, SPP1, and RAC1) from the 17 HAIRG model through the LASSO Cox regression, upregulated genes accounted for 7/8 in tumor tissue, which was shown by a heat map." (PMID 35069936, 2022). "In this study, we conducted the correlation analysis between SPP1 expression and clinical characterize, survival, TMB, MSI, the tumor immune microenvironment, immunotherapy, and GSEA." (PMID 35067176, 2022). "We demonstrate that the tumor-specific FAP+ fibroblasts and SPP1+ macrophages were positively correlated in 14 independent CRC cohorts containing 2550 samples and validate their close localization by immuno-fluorescent staining and spatial transcriptomics." (PMID 35365629, 2022). "MMP1, SDC1, SPP1, and CD24 mRNA declaration was much higher in tumor tissues than in non-tumor tissue." (PMID 35037689, 2022). "Consistent with this, SPP1 and TREM2 expression were significantly increased in the tumor fraction compared to the adjacent normal kidney tissue." (PMID 36180422, 2022). "Two lactate-related genes, namely secreted phosphoprotein 1 (SPP1) and MYC proto-oncogene (MYC), are upregulated by > 4-fold in the tumor samples; in fact, SPP1 has the highest change, 16-fold." (PMID 36091047, 2022). "SPP1 was a well-studied oncogene in HCC, and previous studies were primarily concerned with the role of tumor cell-intrinsic SPP1." (PMID 35958556, 2022). "With marked patient occupancy (GBC6), Macro04 exhibited versatile tumor-promoting roles, including cytokine production (e.g., TNFAIP3, CXCL3), pro-angiogenesis (e.g., VEGFA), and ECM remodeling (e.g., SPP1) 28,36,37." (PMID 36198671, 2022). "A study reported that SPP1 mRNA overexpressed in PTC samples and the intensity of SPP1 staining was corresponding to the tumor size and lateral cervical lymph node metastasis (LNM) in human PTC." (PMID 36510497, 2022). "Our analyses provide an overview of the altered tumor ecosystem in ICC treated with ICBs and highlight the potential role of targeting CAFs and SPP1+TAMs in developing a more rational checkpoint blockade-based therapy for ICC." (PMID 35558087, 2022). "Since SPP1 signaling plays a pivotal role in tumor progression, we analyzed the SPP1 signaling network in T-ICC and P-ICC tumor ecosystems separately." (PMID 35558087, 2022). "Single-cell and spatial analysis of CRC tumor tissues also revealed the close relationship between FAP+ fibroblasts and SPP1+ Møs, and the positivity of both molecules are predictive of less therapeutic benefit from an anti-PDL1 therapy." (PMID 36211375, 2022). "Freshly isolated cells were additionally characterized for specific mRNA expression of tumor (GPC3, SPINK1, SPP1, KPNA2) and fibroblast (COL1A2, TWIST2, FGF7) marker genes using RT–qPCR." (PMID 36077764, 2022). "In this study, we first illustrated that the SPP1 expression in LUAD tissues was significantly increased and was unequal with different tumor stages, invasion depth, and lymph node metastasis." (PMID 36266702, 2022). "To further unveil the spatial patterns of SPP1 expression in GC, we analyzed spatial transcriptomic data obtained from GSE186290, which contained one tumor tissue section from an orthotopic model of GC in mice." (PMID 36612160, 2022). "For further characterization of PHCs, the expression of the following HCC-specific tumor markers was investigated: GPC3, SPINK1, SPP1 and KPNA2." (PMID 36077764, 2022). "The survival result showed the worse prognosis of patients with dual high expression of SPP1 and CD44, indicating the pro-tumor role of the SPP1/CD44 axis in the progress of HCC." (PMID 35958556, 2022). "Secreted phosphoprotein 1 (SPP1), an extracellular secreted glycol phosphoprotein, is closely related to tumor biologies, such as proliferation, migration, and invasion." (PMID 36266702, 2022).
tumor (continued). "We found >85% consistency of the ligand–receptor interactions (i.e., SPP1-PTGER4 and LGALS9-SLC1A5) between tumor cells and TAMs using the two methods, suggesting that the identified pairs are stable." (PMID 36476645, 2022). "After removing the individual samples from the database, we obtained 20 pairs of paired samples and then compared the expression levels of CCL20, SCG5, SPP1, FOLR3, and KRT75 genes in tumor tissues vs. normal tissues." (PMID 36684241, 2022). "Based on data mining of a closely related pro-tumor network between NET score and SPP1 expression level, we further investigated their potential to exert a cooperative effect on cancer behavior." (PMID 35432310, 2022). "The higher expression of FAM3C, LGALS9, ANXA1, SPP1, CD99 and LAMP1 in tumor tissues compared with normal tissues were confirmed by immunohistochemistry in tumors." (PMID 35087839, 2021). "We applied CIBERSORT and xCell to calculate the proportion and abundance of tumor-infiltrating immune cells (TICs) in LUAD, and compared the differences in patients with high or low SPP1 expression and wild-type or mutant EGFR." (PMID 34178613, 2021). "A recent study showed that the high expression of Snail1 in mesenchymal tumor cell induces the expression of several cytokines (CD73, CSF1, SPP1), which collectively expedites the assembly of tumor immunosuppressive microenvironments." (PMID 34917071, 2021). "A cluster of genes that were upregulated in the tumours, compared to normal tissues were COL1A1, COL11A1, SPP1, COMP, SFRP4 and INHBA." (PMID 34824625, 2021). "We also established their prognostic value in more tumor types and found that in most tumors (such as HNSC, BLCA, and SKCM), high expression of FN1 and SPP1 in immune cells were related to poor prognosis." (PMID 34804043, 2021). "On the other hand, SPP1 can induce endothelial cells and upregulate VEGF-induced migration of endothelial cells, having a synergistic effect with VEGF in tumour angiogenesis." (PMID 33962640, 2021). "GAD1, SPP1, and WFS1 were upregulated, whereas GOT2, EHHADH, and APOA1 were downregulated in HCC samples compared with peri-tumor controls, and this was consistent with the results in the ICGC, GSE14520, GSE54236, GSE107170, and GSE36376, validation datasets." (PMID 34869039, 2021). "Secreted phosphoprotein 1 (SPP1) also called as Osteopontin (OPN), it has been reported to be involved in tumor progression, metastasis and suggested as a promising prognosis/therapeutic target biomarker." (PMID 34616672, 2021). "The most consistently upregulated genes across multiple tumor types were TOP2A (FC = 7.8), SPP1 (FC = 7.0) and CENPA (FC = 6.03), and the most consistently downregulated gene was ADH1B (FC = 0.15)." (PMID 33807717, 2021). "Past studies showed that CXCL13, IDO1, PI3, SPP1 and TRIM22 were closely correlated with the prognosis, immunization and chemotherapy sensitivity of tumor." (PMID 34736480, 2021). "Notably, we established a novel six‐gene (APOC1, GLTP, ISG20, SPP1, SLC24A3 and UPP1) prognostic signature and discovered for the first time that this signature was associated not only with intrinsic aggressive features but also with the tumour immune microenvironment." (PMID 34498424, 2021). "The immunofluorescent staining of our local clinical tumor tissue section analyses also showed that the expression of YAP1, LOX, CD68 (human macrophage marker), SPP1, and PD-L1 was enhanced in HSPA7-high GBM tissues compared to HSPA7-low tissues." (PMID 34354698, 2021). "Compared with peri-tumor samples, GAD1, SPP1, and WFS1 were significantly upregulated in tumor tissues, and GOT2, EHHADH, and APOA1 were significantly downregulated in tumor tissues." (PMID 34869039, 2021). "SPP1 is one of the signature genes elevated in HCC tissues and closely related to the tumor process." (PMID 33568167, 2021).
tumor (continued). "The single-cell RNA-seq analysis of the SCCHN TMI genes revealed that four of these genes (MASP1, EGFL6, SPP1, and P4HA1) are expressed in subpopulations of fibroblasts, macrophages, T cells and in tumor cells." (PMID 34830910, 2021). "UALCAN analysis indicated that the transcription levels of GAD1, SPP1, and WFS1 were markedly higher in HCC tissues than in peri-tumor control tissues in the subgroup analyses." (PMID 34869039, 2021). "Similar to previous studies, SPP1, MTHFD2, TRIP13, MKI67, MMP9, and KLF4 were some of the most clinically valuable tumor markers, especially in CC and EC." (PMID 34834529, 2021). "The expression of GAD1 (r = -0.14, P = 9.2E-03) and SPP1 (r = -0.237, P = 8.32E-06) was negatively correlated, whereas EHHADH was positively correlated (r=-0.15, P =5.36E-03) with tumor purity." (PMID 34869039, 2021). "To further verify the results of bioinformatics analysis, we applied qRT-PCR to validate the mRNA levels of HMMR, SPP1, FN1, CCNB1, CXCL8, MAD2L1 and CCNA2 in 10 paired tumor and adjacent normal tissues with qRT-PCR." (PMID 34126961, 2021). "SPP1, CRYAB, NNMT and HILPDA were highly expressed in tumour cells (ccRCC1); GSTA2, BHMT and ADSSL1 were highly expressed in tumour cells 1 (ccRCC2); and HIF1A-AS2, DNAH11 and EGOT were highly differentially expressed in tumour cells 2 (ccRCC2)." (PMID 34168986, 2021). "SPP1 in turn acted as a T-cell inhibitory ligand through ligation with the CD44 molecule, inhibiting tumour cell cytotoxicity and promoting cancer progression." (PMID 33187209, 2020). "The overexpression of SPP1 and ANGPT2 in EC tissue samples also indirectly confirmed that abnormal tumor angiogenesis was closely related to the occurrence of EC by activating the tumor angiogenesis." (PMID 32908897, 2020). "In the case of PyMT tumor cells, higher levels of Ltf, Spp1, Anxa1 and Cldn4 distinguish them from Neu and BRCA1-null tumor cells, and some of these genes have been associated with luminal progenitors." (PMID 32840210, 2020). "To verify the reliability of these bioinformatics evaluations, we carried out RT-qPCR to assess expression of hub genes (BGN, SPP1, LINC01614, and LINC01415) in clinical tumor samples." (PMID 33362844, 2020). "The results were displayed a heatmap, which showed the expression levels of P3H1, SPP1, MMP1, LGALS1, and ITGB5 in tumor tissues and normal tissues." (PMID 32951492, 2020). "These suggested that SPP1 exerts a vital part in TAMs, M2, and TIM-3 polarization and promoting tumor progression and metastasis in COAD, HNSC, LUAD, and LUSC." (PMID 33324676, 2020). "Expression of BGN, SPP1, LINC01415, and LINC01614 was much higher in tumor samples than in normal esophageal tissues." (PMID 33362844, 2020). "In GBM, SPP1 is secreted by healthy stromal astrocytes and in the perivascular niche of proneural GBM, where it promotes stemness and radio resistance in tumor cells." (PMID 33066172, 2020). "Both SPP1 and OPN have been identified as markers for progression and the poor survival of BrC patients, promoting tumor cell proliferation, angiogenesis, migration, invasion and bone metastasis." (PMID 32722549, 2020). "CXCL5, ELN, JUN, and FGFR4 were highly expressed in normal tissues, while PLAU, RNASE7, JAG1, SPP1, and TNFRSF18 were highly expressed in tumor tissues." (PMID 32699529, 2020). "The relationship between SPP1 and immune infiltration in LUAD was analyzed by the Tumor Immune Estimation Resource (TIMER) database." (PMID 32595698, 2020). "The quantification results suggested that COL1A1, COL3A1, SPP1, and THBS2 protein levels were significantly increased in GC tumor tissues compared to normal adjacent tissues." (PMID 33665169, 2020). "High expression of SPP1, BGN, LINC01614, and LINC01415 in tumor samples was validated further by RT-qPCR." (PMID 33362844, 2020).